OCLN (occludin)
Diseases named in the same sentence as OCLN in open-access papers (continued):
Sharing a sentence is not in itself a finding about the gene and the disease.
Testicular atrophy (2 papers, 2015 to 2016). Wasting (atrophy) of the testicle (the male gonad) manifested by a decrease in size and potentially by a loss of fertility. "Occludin knockout mice suffer from testicular atrophy with progression of age." (PMID 27486954, 2016).
thyroid cancer (2 papers, 2024 to 2025). "Occludin staining was unrelated to parameters of tumor aggressiveness in breast, gastric, endometrial, and thyroidal cancer." (PMID 40173205, 2025).
varicocele (2 papers, 2016 to 2021). A condition characterized by the dilated tortuous veins of the spermatic cord with a marked left-sided predominance. "Obviously, the changes in TJ protein (Occludin, Claudin-11, and ZO-1) expression caused by varicocele and MOP are the result of complicated biological events." (PMID 28090212, 2016). "Animals lacking PPAR-α and TLR4 receptors showed reduced expression of claudin-11 and occludin when subjected to varicocele." (PMID 33668991, 2021). "As a result, we believe that TGF-β3 and TNF-α might be involved in the downregulation of TJ proteins, Occludin, Claudin-11, and ZO-1, and in the damage of the TJ structure that occurred in experimental varicocele." (PMID 28090212, 2016). "Overall, our results suggest that, in line with our previous study, PEA-um, via a TLR4-dependent pathway, selectively restores the expression of claudin-11 and occludin and reduces the expression of TGF-β3, p-ERK 1/2 and NLRP3 in varicocele mice." (PMID 33668991, 2021).
vitamin A deficiency (2 papers, 2021 to 2023). Deficiency of vitamin A due to malnutrition, malabsorption, or dietary lack. "Vitamin A deficiency caused a colon-intestinal barrier in mice, which not only reduced the secretion of immunoglobulin A, but also down-regulated the colon-tight-junction-related protein Occludin and Claudin-1." (PMID 38136169, 2023). "The results show that vitamin A deficiency decreased the ADG, villus height, villus height/crypt depth ratio and mRNA expression levels of IL-22, Occludin and ZO-1." (PMID 34071204, 2021).
acute leukemia (1 paper, 2011). A clonal (malignant) hematopoietic disorder with an acute onset, affecting the bone marrow and the peripheral blood. "Our findings suggest that the degradation of tight junction proteins ZO-1, claudin-5 and occludin by MMP-2 and -9 secreted by leukemic cells constitutes an important mechanism in the BBB breakdown which contributes to the invasion of leukemic cells to the CNS in acute leukemia." (PMID 21857898, 2011).
acute respiratory distress syndrome (1 paper, 2021). Progressive and life-threatening pulmonary distress in the absence of an underlying pulmonary condition, usually following major trauma or surgery. "Similarly, we also observed similar enhanced ADORA2B (3.33 ± 0.67 to 16.12 ± 5.89, p < 0.05) and decreased occludin (81.2 ± 0.3 to 13.3 ± 0.4, p < 0.05) levels in human Acute respiratory distress syndrome lungs." (PMID 33778007, 2021).
Aicardi–Goutières syndrome (1 paper, 2020). "Of these, 33 had Aicardi–Goutières syndrome, 6 had OCLN-related pseudo-TORCH syndrome and 3 had a COL4A1-related disease." (PMID 32895508, 2020).
amyotrophic lateral sclerosis (1 paper, 2012). Amyotrophic lateral sclerosis (ALS) is a neurodegenerative disease characterized by progressive muscular paralysis reflecting degeneration of motor neurons in the primary motor cortex, corticospinal tracts, brainstem and spinal cord. "In the superoxide dismutase-1 mutant rat model of amyotrophic lateral sclerosis, IgG is also reported in the lumbar spinal cord and cortex, although interestingly at the pre-symptomatic stage prior to changes in occludin and increased penetration of Evans Blue dye." (PMID 22713725, 2012).
anaplastic thyroid carcinoma (1 paper, 2020). "Spheroids obtained from anaplastic thyroid carcinoma cells were indicated to possess increased E-cadherin expression in comparison with monolayer, while the expression of tight junction proteins (occludin and ZO-1) was lost." (PMID 33291824, 2020).
Atrophy (1 paper, 2025). Any weakening or degeneration, especially through lack of use. "Ligustilide treatment reduced DSS-triggered weight loss, increased DAI scores, reduced spleen enlargement and thymic atrophy, increased colon length, restored colonic pathological structure, increased expressions of ZO-1 and Occludin, and decreased EGR1 downstream target protein ADAM17 expression." (PMID 40904624, 2025).
attention deficit-hyperactivity disorder (1 paper, 2024). A disorder characterized by a marked pattern of inattention and/or hyperactivity-impulsivity that is inconsistent with developmental level and clearly interferes with functioning in at least two settings (e.g. at home and at school). "detected higher zonulin and occludin levels in pediatric patients with attention deficit hyperactivity disorder compared to a control group." (PMID 39109367, 2024).
Azoospermia (1 paper, 2022). Absence of any measurable level of sperm,whereby spermatozoa cannot be observed even after centrifugation of the semen pellet. "In nonobstructive azoospermia patients, claudin-11, occludin, and ZO-1 are associated with increased apoptosis and unstained/irregular TJ development." (PMID 36071829, 2022).
Baraitser-Reardon syndrome (1 paper, 2025). "This subtype (also called Baraitser-Reardon syndrome) is caused by biallelic mutations in OCLN, which encodes occludin, a tight-junction protein critical for blood-brain barrier integrity." (PMID 40937018, 2025).
behavioural disorders (1 paper, 2025). "Moreover, LIPUS preserved intestinal barrier function by upregulating the levels of occludin and zonula occludens, decreasing the levels of lipopolysaccharide (LPS) and LPS-binding protein in serum, and ameliorating behavioural disorders." (PMID 40170911, 2025).
bladder tumor (1 paper, 2022). "Moreover, immunofluorescence staining showed the fluorescence intensities of OCLN in the bladder tumor cells were significantly reduced after being treated with rPEDF." (PMID 35992356, 2022).
breast adenocarcinoma (1 paper, 2020). "An elevated level of occludin in spheroids of lung and breast adenocarcinoma cell lines was shown in a number of works." (PMID 33291824, 2020).
calcification (1 paper, 2014). Process by which organic tissue becomes hardened by the physiologic deposit of calcium salts. "Recently, it has been reported that mutations of occludin cause brain calcification and renal dysfunction, which further suggests the occludin involvement in TJ barrier function." (PMID 25063198, 2014).
cerebral cavernous malformation (1 paper, 2022). A disorder characterized by malformations in the structure of the capillaries in the brain. "Interestingly, gene mutations in endothelial junctional proteins occludin, junctional adhesion molecule 3 (JAM3) and cerebral cavernous malformation (CCM) −1, −2, −3 lead to the BBB deficiency and brain calcification." (PMID 35309892, 2022).
Cholestatic liver disease (1 paper, 2024). "Immunofluorescence of p16 and occludin, a tight junction protein expressed in IECs,20 confirmed these as the main senescent cells in the intestine during cholestatic liver disease." (PMID 39314550, 2024).
chorioamnionitis (1 paper, 2014). A morphologic finding indicating inflammation of the fetal sac membranes. "Histological chorioamnionitis with fetal involvement has been considered a possible risk factor for NEC and inflammation associated with this pregnancy complication may lead to occludin endocytosis and therefore reduced migration of γδ IEL into the intraepithelial compartment." (PMID 24905458, 2014).
choroid plexus carcinoma (1 paper, 2012). A malignant neoplasm arising from the choroid plexus. "Localization of occludin to punctate strands between adjacent cells along with weak expression and cytoplasmic localization of E-cadherin has been reported in CPC-2 human choroid plexus carcinoma cells and attributed to dysregulation of AJs." (PMID 23288986, 2012).
CNS leukemia (1 paper, 2011). "In conclusion, our results established a correlation between MMP-2 and -9 secreted by leukemic cells and the disruption of the TJ proteins ZO-1, claudin-5 and occludin, which increases paracellular permeability of leukemic cell across the BBB in CNS leukemia." (PMID 21857898, 2011).
cognitive decline (1 paper, 2025). "We also show that both N-cadherin contacts and occludin TJs are impaired in the brain vessels of middle-aged individuals, further indicating their contributing roles in the mechanisms of physiological aging and cognitive decline." (PMID 40503940, 2025).
cutaneous squamous cell carcinoma (1 paper, 2019). "A frequent complete loss of occludin was reported in cutaneous squamous cell carcinoma as compared to the precursor lesions and sun-exposed skin, which might result in decreased epithelial cell-cell adhesion and reduction of susceptibility to apoptosis." (PMID 31754355, 2019).
cystic fibrosis (1 paper, 2024). Autosomal recessive disorder caused by pathogenic variants in the CFTR gene (cystic fibrosis transmembrane conductance regulator), which encodes a chloride and bicarbonate channel expressed in epithelial cells, and follow the diagnosis criteria. "In accordance with our observation of nuclear localization of occludin, it was also found in astrocytes, in epithelial intestinal cells, and in cystic fibrosis airway epithelial cells." (PMID 38786035, 2024).
dementia (1 paper, 2025). Loss of intellectual abilities interfering with an individual's social and occupational functions. "Moreover, compared with Scop-FM group, transplantation of XSB-FM markedly boosted the AB-PAS positive cells in the intestinal mucosa, and upregulated ZO-1 (p < 0.05) and Occludin (p < 0.05) protein expressions in dementia mice induced by scopolamine." (PMID 40689211, 2025).
demyelinating peripheral neuropathies (1 paper, 2018). "In a small study on peripheral nerve biopsies of five patients with demyelinating peripheral neuropathies, claudin-1, and occludin were measured in Western blot and localized by immunolabeling." (PMID 30618565, 2018).
dermatitis (1 paper, 2026). An inflammatory process affecting the skin. "Topical application of 1% K-7-G significantly alleviated AD-like symptoms in a mouse model, decreasing dorsal skin thickness, dermatitis score, and scratching frequency while restoring the expression of filaggrin, loricrin, and occludin (p < 0.0001)." (PMID 42075836, 2026).
diarrhoea (1 paper, 2013). "Campylobacter jejuni is a gut bacterium that causes diarrhoea by disrupting tight junctions, which is associated with Jun Kinase activation and redistribution of Occludin from the cell surface to an intracellular region." (PMID 23685254, 2013).
Dyskinesia (1 paper, 2025). A movement disorder which consists of effects including diminished voluntary movements and the presence of involuntary movements. "Electroacupuncture stimulation at DU24, ST25, ST37 (upper giant vacuole), and LI11 in rotenone-induced mice increased the expression levels of ZO-1 and occludin, decreased permeability, and attenuated dyskinesia and gastrointestinal inflammation." (PMID 40390763, 2025).
embryonal carcinoma (1 paper, 2021). A non-seminomatous malignant germ cell tumor characterized by the presence of large germ cells with abundant cytoplasm resembling epithelial cells, geographic necrosis, high mitotic activity, and pseudoglandular and pseudopapillary structures formation. "HNF4α triggered formation of the functional TJPs occludin and claudin-6/7 and the establishment of polarized epithelial morphology in F9 embryonal carcinoma cells." (PMID 34819492, 2021).
endometriosis (1 paper, 2021). The growth of functional endometrial tissue in anatomic sites outside the uterine body. "Well in line with the literature, we observed occludin and claudin-5 protein changes in the brain harvested from the endometriosis rats." (PMID 34064310, 2021).
ependymoma (1 paper, 2017). A WHO grade II, slow growing tumor of children and young adults, usually located intraventricularly. "Furthermore, we could not detect expression of claudin-1 and −2, occludin or E- and N-cadherin in these cases suggesting that claudin-5 expression delineates a specific subset of ependymoma cases." (PMID 27395057, 2017).
Erythema (1 paper, 2025). Redness of the skin, caused by hyperemia of the capillaries in the lower layers of the skin. "By suppressing this inflammatory cascade, ERG was able to alleviate erythema and restore the integrity of the skin’s physical barrier, evidenced by the restored expression of key tight junction proteins Claudin-1, Occludin, and ZO-1." (PMID 41295413, 2025).
Ewing sarcoma (1 paper, 2025). A small round cell tumor that lacks morphologic, immunohistochemical, and electron microscopic evidence of neuroectodermal differentiation. "Earlier studies confirmed occludin protein expression in small subsets of Ewing sarcomas and reported occludin mRNA expression from osteoblasts and osteosarcoma cell lines." (PMID 40173205, 2025). "For example, unequivocal occludin staining was identified in 34.7% (9.7% strong) of Hodgkin’s lymphomas, 47.1% (18.8%) of Ewing sarcomas, 6.9% (2.3%) of leiomyosarcomas, and in 10.5% (5.3%) of osteosarcomas." (PMID 40173205, 2025).
Fulminant hepatic failure (1 paper, 2009). Hepatic failure refers to the inability of the liver to perform its normal synthetic and metabolic functions, which can result in coagulopathy and alteration in the mental status of a previously healthy individual. "Reductions in levels of the tight junction protein, occludin, in intestinal epithelial cells may be caused by the production of TNF-α in mice with fulminant hepatic failure." (PMID 19772664, 2009).
gastric ulcer (1 paper, 2023). An ulcerated lesion in the mucosal surface of the stomach. "Both HCl/ethanol- and indomethacin-induced gastric ulcers showed increased TNF-α, IL-6, Evans blue permeation, and PECAM-1, and decreased COX-2, PGE2, occludin, and LPA5 receptor expression levels." (PMID 38069044, 2023).
gestational diabetes (1 paper, 2021). Carbohydrate intolerance first diagnosed during pregnancy. "Our study aimed to investigate the effects of gestational diabetes mellitus (GDM), and its treatment, on endothelial junctional integrity, gene and protein expression of occludin splice variants, and potential regulation of expression by microRNAs (miRNAs)." (PMID 33001231, 2021).
Glucose intolerance (1 paper, 2020). Glucose intolerance (GI) can be defined as dysglycemia that comprises both prediabetes and diabetes. "Sucralose increased the abundance of B. fragilis in particular, resulting in a decrease in the abundance of occludin and an increase in proinflammatory cytokines, glucose intolerance, fatty acid oxidation and ketone bodies." (PMID 32804018, 2020).
head and neck cancer (1 paper, 2025). A primary or metastatic malignant neoplasm affecting the head and neck. "In a mouse model, radiation treatment for head and neck cancer often results in upregulation of occludin; which might be complicated by oral mucositis." (PMID 39996934, 2025).
head and neck squamous cell carcinoma (1 paper, 2022). A squamous cell carcinoma that arises from any of the following anatomic sites: lip and oral cavity, nasal cavity, paranasal sinuses, pharynx, larynx, and salivary glands. "As a positive control for Occludin immunohistochemistry, we used a tissue section from a xenograft head and neck squamous cell carcinoma generated with UM-SCC-1 cells that shows clear staining for Occludin at the cell membrane." (PMID 36340037, 2022).
Hematochezia (1 paper, 2021). The passage of fresh (red) blood per anus, usually in or with stools. "Our results indicated that atractylodin could reduce the weight loss of mice with UC, control diarrhea and hematochezia, alleviate trauma to the colon, reduce the loss of colonic goblet cells, and increase the expression of MUC2, ZO-1, and occludin." (PMID 34335244, 2021).
hemorrhage (1 paper, 2022). Loss of blood from the vascular compartment to the exterior or into nonvascular body space as a result of rupture or severance of the blood vessels. "Previous studies indicated that AIS patients with increased serum occludin levels at baseline had a high risk of hemorrhage transformation, regardless of non‐reperfusion therapy or reperfusion therapy." (PMID 35338575, 2022).
hemorrhagic stroke (1 paper, 2020). A stroke caused by a bleed on the brain. "We further investigated the difference of serum occludin levels between AIS and hemorrhagic strokes." (PMID 33269096, 2020).
Hodgkins lymphoma (1 paper, 2025). A heterogeneous group of malignant lymphoid neoplasms of B-cell origin characterized histologically by the presence of Hodgkin and Reed-Sternberg (HRS) cells in the vast majority of cases. "Notably, occludin positivity was seen in 34.7% of 72 Hodgkin’s lymphomas." (PMID 40173205, 2025).
hypertriglyceridemia (1 paper, 2025). A laboratory test result indicating elevated triglyceride concentration in the blood. "It has been postulated that hypertriglyceridemia and high plasma LPS associated with HFD may be due to decreased expression of intestinal epithelial proteins such as Occludin and ZO-1 secondary to increased intestinal permeability." (PMID 40444056, 2025).
Hypoglycemia (1 paper, 2015). A decreased concentration of glucose in the blood. "The results clearly showed that hypoglycemia significantly downregulated the expression of claudin-5 in bEnd.3 cells, without affecting ZO-1 and occludin expression and distribution." (PMID 25761767, 2015). "However, hypoglycemia did not significantly change ZO-1 and occludin expression compared to the control (5.5 mM glucose)." (PMID 25761767, 2015).
Hyponatremia (1 paper, 2025). An abnormally decreased sodium concentration in the blood. "Real-time PCR was used to measure mRNA expression levels for claudin-5, occludin, and ZO-1 in the cortex in acute and chronic hyponatremia—induced by either vasopressin or desmopressin." (PMID 40603486, 2025). "Levels of occludin mRNA were significantly reduced in acute hyponatremia-induced by both AVP (p < 0.001, n = 8) and dDAVP (p < 0.001, n = 6), vs. Sham group (n = 7)." (PMID 40603486, 2025). "In the absence of functional BBB dysfunction, a surprising result was decreased occludin, claudin-5, and zonula occluden-1 gene expression in acute AVP-induced hyponatremia." (PMID 40603486, 2025).
imbalance (1 paper, 2023). "After Pte treatment, the expression levels of ZO-1 and occludin in the hippocampus significantly increased, suggesting that Pte hindered the progression of immune imbalance and oxidative stress." (PMID 37267263, 2023).
infectious diarrhea (1 paper, 2017). "The reduction of Occludin, Claudins, ZOs and other tight junctions may induce IBD, IBS and infectious diarrhea." (PMID 29190890, 2017).
influenza infection (1 paper, 2021). "Previous influenza infection was associated with decreased claudin-1 expression in all groups and decreased occludin expression in OVA or HDM-challenged mice." (PMID 34445491, 2021). "This suggests a possible association with influenza infection and sensitization where a compensatory effect of claudin-1 is seen as occludin expression is lost." (PMID 34445491, 2021). "In contrast, strong occludin expression within the airway epithelium has been previously reported; however, the present data demonstrate a loss in protein expression following influenza infection and OVA or HDM challenge." (PMID 34445491, 2021). "To investigate the direct in vivo effects of influenza infection on barrier integrity, we examined the TJs claudin-1 and occludin, key junctional proteins for the maintenance of epithelial integrity via immunohistochemical staining." (PMID 34445491, 2021).